IL10 (interleukin 10)
Diseases named in the same sentence as IL10 in open-access papers (continued):
Sharing a sentence is not in itself a finding about the gene and the disease.
tumor (continued). "Tumor-promoted Th2 polarization can suppress T cell anti-tumor response by secreting IL-4, IL-5, and IL-10; in fact, untreated or progressive BC is associated with lower levels of IFN-γ and IL-2 and higher levels of Th2 cytokines." (PMID 39682686, 2024). "Tregs within the tumor can produce cytokines such as IL-4, IL-10, and IL-13, causing monocytes to differentiate into tumor-associated macrophages (TAMs)." (PMID 39253716, 2024). "Constrained Il10 transcription limits the risk of instigation of the host immune system towards tumor-promoting type 2 phenotype." (PMID 38649988, 2024). "Studies have indicated that it is associated with high expression of TGF-β, IL-4, IL-13, and IL-10, suppressing the inflammatory response and encouraging tumor angiogenesis and distant metastasis." (PMID 39108265, 2024). "A study of routine IL-10 exposure to acute otitis media (AOM) found that tumor diversity was strongly associated with colitis." (PMID 38415245, 2024). "Due to its potent ability to suppress anti-tumour immunity, IL-10 is associated with poor prognosis across a broad range of human cancers as shown by recent meta-analyses encompassing multiple solid and haematological cancer types." (PMID 38464388, 2024). "Under inflammatory stimuli such as transforming growth factor-β (TGF-β), IL-6, and interleukin-10 (IL-10), tumor-associated macrophages (TAMs) are more likely to transition from the anti-tumor M1 phenotype to the pro-tumor M2 phenotype." (PMID 39290325, 2024). "Egfl6 induces phosphorylation of Syk to promote activation of IL-10 and Cxcl2 in tumor-associated myeloid cells to drive immunosuppression." (PMID 39312740, 2024). "Increased IL-10 has been associated with worse outcomes in both tumor clearance and trauma recovery, highlighting the need for a deeper understanding of how traumatic injuries can differentially impact specific patient populations." (PMID 38903094, 2024). "High levels of IL10 in the tumor microenvironment have been associated with immunosuppression and reduced response to immunotherapy." (PMID 39050251, 2024). "Tumor-associated macrophages (TAMs) release various cytokines, including IL-8, IL-6, and IL-10, which regulate the cell cycle and promote tumor growth." (PMID 38402232, 2024). "The most enriched gene sets corresponded to signatures characteristic of an immunosuppressive microenvironment, particularly IL-10 signaling and tumor-associated macrophages, mast cells, and B cells, as well as cell cycle–related gene sets." (PMID 38815867, 2024). "Simultaneously, IH-induced tumor cells release interleukin 10 and promote M2-type differentiation of tumor-associated macrophages (TAMs), which exhibit immunosuppressive properties." (PMID 38605948, 2024). "One mechanism for this immune suppression is that the expression of CD200 on tumor cells enhances the release of IL-10 by tumor-associated myeloid cells, contributes to immune suppression and favors tumor progression and recurrence." (PMID 39795972, 2024). "This construct intends to better deliver IL-10 in tumor-associated macrophages (TAMs) since CSF1R is highly expressed in TAMs." (PMID 39204319, 2024). "IL-10 and IL-4 are confirmed immunosuppressive cytokines associated with tumor growth and metastasis." (PMID 39439459, 2024). "Remarkably, these macrophage cells are differentiated into the M2d subset, making up the main component of tumour-associated macrophages (TAMs), as measured by upregulated Il-10 and Vegf mRNA." (PMID 38169974, 2024). "Tumor-infiltrating M2-type macrophages then inhibit the antigen-presenting ability of dendritic cells (DCs) by producing IL-10 and prevent DCs from activating CTLs, thereby causing dysfunction of DCs in the TME." (PMID 39403370, 2024). "This hybrid phenotype is implicated in tumor immune evasion because it has the ability to secrete IL-10." (PMID 37283734, 2023). "Tregs, in turn, are recruited into the TME by tumor-associated neutrophils and macrophages, partly by KC-derived IL-10." (PMID 36831649, 2023).
tumor (continued). "IL-10, an immunoregulatory component, has been implicated in promoting tumor malignancy by influencing T-cell apoptosis and tumor cell survival." (PMID 37816585, 2023). "Tumours have been reported to release growth factors such as M-CSF, and cytokines including IL4 and IL10, which initiate differentiation of macrophages into tumour-associated macrophages (TAMs)." (PMID 37893161, 2023). "Macrophages associated with the tumor produce IL-10 and secrete extracellular matrix proteases and serine protease associated with the most advanced degrees of tumor and metastasis." (PMID 36946842, 2023). "For instance, the systemic immune inflammation index, and the levels of tumor‐infiltrating immune cells, urinary IL‐10, serum cytotoxic T‐lymphocyte‐associated protein 4 (CTLA‐4), and transcription factors can predict BCG response." (PMID 38107059, 2023). "Tumor subsite and baseline social eating, stress (hyperarousal), coughing, feeling ill, and IL-10 were associated with the course of SumSc." (PMID 37432446, 2023). "We also found that FJX1 expression is positively associated with TGFB1 and IL-10, which can induce macrophages to M2 polarization and regulate tumor immunology." (PMID 37324001, 2023). "For example, HSP27 shows biological effects on monocytes by causing IL10 and TNFα secretion and blocking monocyte differentiation to normal dendritic cells and tumor-associated macrophages to promote cancer progression and chemoresistance." (PMID 37893013, 2023). "This process is mediated by IL-6 which contributes to the recruitment of tumor-associated macrophages of the M2 immunosuppressive subtype, which in turn, upregulates anti-inflammatory cytokines including IL-10 and TGF-β." (PMID 38188300, 2023). "M2 tumor-associated macrophages (TAMs) promote tumor progression by producing immunosuppressive cytokines such as IL-10 and TGF-β." (PMID 37036489, 2023). "LGALS1, the gene encoding Gal-1, promotes M2 TAMs secretion of IL-10 and TGFβ, which contribute to a tumor-supporting and immunosuppressive environment." (PMID 37759870, 2023). "Conversely, M2 TAMs exert tumor-supporting effects by secreting immunosuppressive cytokines such as IL-10, and high abundances of M2 TAMs are associated with a poor prognosis." (PMID 36693898, 2023). "In counterpart, M2 TAMs have an anti-inflammatory and tumor progression promoter phenotype, they generate IL-10, IL-4, IL5, VEGF, and they cause immune suppression promoting transforming growth factor β (TGF-β)." (PMID 37190507, 2023). "Among various constitutively- and BCR/CD40-mediated factors secreted, tumour subsets co-express two important immunoregulatory cytokines, IL10 and TGFβ1, both associated with a memory B cell phenotype." (PMID 36973425, 2023). "Our result is consistent with a previous report demonstrating that IL-10 produced by tumor-associated macrophages type-2 (TAM2) reduces the number of CD103-expressing DCs." (PMID 37202419, 2023). "Tumor-associated macrophages (TAMs) often exhibit an M2-like phenotype with high expression of immunosuppressive molecules such as IL-10." (PMID 37801479, 2023). "The characteristics of tumor-associated M2 macrophages are orchestrated by the action of IL-4, IL-10, IL-13, macrophage colony-stimulating factor 1 (CSF-1), CCL2, or VEGF-A." (PMID 38033495, 2023). "We evaluated IL-10-producing CD68+ tumor-associated macrophages (TAMs) in cancer tissue from GC patients." (PMID 37153541, 2023). "Increased IL-10 expression in primary tumor cells and tumor-associated macrophages has been proposed as a predictor of cancer stage progression and metastatic potential development." (PMID 37359549, 2023). "Their differentiation is stimulated by Transforming Growth Factor (TGF)-beta and Interleukin (IL)-10 produced by tumour-associated macrophages and other types of cells of the tumour microenvironment." (PMID 37509293, 2023).
tumor (continued). "PD-1 hi B cells suppress tumor-specific T-cell response via IL10-dependent pathways upon interacting with PD-L1 to cause T-cell dysfunction and disease progression." (PMID 37046842, 2023). "Although multiple effector molecules have been reported, IL-10 is considered the main mediator of tumor-associated Breg function." (PMID 37291146, 2023). "ROS secreted by MDSCs and interleukin (IL)-4, IL-10, and IL-13 secreted by T helper (Th)-2 cells stimulate M2 tumor-associated macrophage (TAM) proliferation." (PMID 36831498, 2023). "In the TME, tumor-associated factors such as adenosine favor the differentiation of M2d macrophages with high expression of IL-10 and VEGF." (PMID 37251409, 2023). "Immunosuppressive B cells that produce IL-10 are linked to a tumour microenvironment that releases high levels of pro-inflammatory stimuli." (PMID 37398676, 2023). "For example, tumor-associated MΦ release the immunosuppressive cytokine IL-10 or induce local depletion of arginine and tryptophan which are needed for T-cell activation and polarization." (PMID 37435060, 2023). "Monocytes infiltrate the tumor and differentiate into tumor-associated macrophages (TAMs), which secrete IL-10 into the tumor microenvironment, creating a suitable environment of immunosuppression for tumor progression." (PMID 37371050, 2023). "Malignant cells productions, like TGF-β, VEGF, and IL-10 can trigger the DCs dysfunction, which leads to the ineffective presence of tumor-associated antigens in lymphocytes." (PMID 37735675, 2023). "Quantitative PCR (qPCR) of whole tumor lysate for transcript levels of the cytokines TGFβ (Tgfb1–2), IL10 (Il10), and IL35 (Ebi3 and Il12a), associated with suppressed antitumor immunity, showed reduced levels in Vegfr2Y1173F/+ tumors." (PMID 37651195, 2023). "Treg NKT cells predispose patients to tumor growth and progression via the inhibition of T cell function through the secretion of IL-10 and TGF-β." (PMID 37766141, 2023). "Immunosuppressive factors, such as TGF-β, IL-6, IL-10, and IL-23 secreted by MDSCs, TAMs, and Tregs, suppress NK cell function, causing cancer-immune evasion and promoting tumor progression." (PMID 36769116, 2023). "IL-10 has the ability to induce M2 polarization of tumor-associated macrophages, thus promoting tumor growth in RCC." (PMID 38006403, 2023). "IL10 also promote the development and proliferation of tolerogenic DCs, tumor-associated macrophages (TAMs), and MDSCs that populate the tumor microenvironment—to support angiogenesis immune escape of cancer cells." (PMID 36901714, 2023). "IL-6 then orchestrates recruitment of tumor-associated macrophages of the M2 suppressive phenotype which produce anti-inflammatory cytokines like IL-10 and TGF-β, which in turn inhibit tumor-associated T-cell invasion and activation." (PMID 38188300, 2023). "The presence of a variant allele G in tumor tissue is positively associated with elevated IL-10 mRNA levels." (PMID 37077342, 2023). "The primary tumor also contains tumor-associated macrophages (TAM) that promote a “pro-tumor” environment by producing anti-inflammatory cytokines such as IL-10 and TGF-beta via the stimulation of IL-13 and IL-4." (PMID 36769180, 2023). "In patients with GC, IL-10 secreted by tumor-associated macrophages regulates the proliferation and invasion of GC cells via c-mesenchymal epithelial transition protein/STAT3 signaling." (PMID 37946227, 2023). "Proinflammatory CD80, CXCL10, anti‐inflammatory IL‐10, and the tumor‐associated markers MMP2, MMP7, MMP12, and MGLL showed lower baseline expression and were upregulated in macrophages as well." (PMID 38037545, 2023). "A NSCLC clinical study found that a subset of tumor-infiltrating B7-H3+ CD14+ HLA-DR−/low M-MDSCs secrete elevated amounts of IL10 and are associated with reduced recurrence-free survival." (PMID 37830618, 2023).
tumor (continued). "The course of SumSc from baseline to 24 months was significantly associated with tumor subsite, social eating, stress (hyperarousal), coughing, feeling ill, and IL-10, as measured at baseline." (PMID 37432446, 2023). "Tumor-associated macrophages (TAMs) in late-stage cancer are characterized by an M2-like phenotype (low IL-12 and high IL-10 expression) and potentiate tumor progression through decreased tumoricidal activity, angiogenesis, and matrix remodeling." (PMID 36428749, 2022). "These mice also showed a decrease in interleukin-10 (IL-10) at the mRNA level, which is indicative of regulatory T cells associated with poor anti-tumor response." (PMID 36033452, 2022). "Several immunosuppressive cytokines, including IL-10 and IL-4, are secreted from tumor cells and known to polarize TAMs to a pro-tumor phenotype and are associated with poor patient prognosis." (PMID 35267548, 2022). "We also found that knocking out ALKBH5 activates the immune system with more antitumor-associated cytokines (IFN-γ, IL-2) and fewer pro-tumor-associated cytokines (IL-10, IL-13)." (PMID 36566230, 2022). "For example, a protumorigenic PD-1hi Breg subset in human HCC exhibited a unique CD5hiCD24−/+CD27hi/+CD38dim phenotype, which caused T-cell dysfunction and fostered tumor progression via IL-10-dependent pathways." (PMID 35967441, 2022). "In such tumor-promoting immune environments, Th2 cells are found to have a regulatory profile associated with high levels of IL-10 and TGF-β." (PMID 35657353, 2022). "We recently reported that the crosstalk between myeloid cells and reactive astrocytes in the tumor microenvironment was linked to IL10 release, mediated by IFN-gamma-JAK/STAT signaling." (PMID 35177622, 2022). "For example, cytokines in the TME, such as TNF-α, IL-6, and IL-8, are associated with angiogenesis and tumor metastasis, whereas IL-4, IL-13, and IL-10 are associated with immune response suppression." (PMID 35844605, 2022). "Activated B cells, on the other hand, are relatively resistant to inhibition by tumor-associated immunosuppressive factors such as IL-10, TGF-β and VEGF." (PMID 36159874, 2022). "The development of tumors is promoted by cytokines G-CSF, IFNγ, TNFα, IL-10, and IL-12p70 released by neoplastic cells and tumor-associated macrophages (TAM)." (PMID 35463072, 2022). "Subsequently, the tumor-associated macrophages (TAMs) promote angiogenesis, tumor progression, metastasis, and resistance to chemotherapy under the influence of IL-4, IL-10, or IL-13." (PMID 36295075, 2022). "It has been reported that tumor associated M2-type macrophages produce IL-10 to weaken the anti-tumor immunity in various cancer types." (PMID 36248808, 2022). "For instance, tumor-associated macrophages indicated an unfavorable prognosis because of the immune events they triggered, such as secreting cytokine interleukin-10 (IL-10)." (PMID 36072600, 2022). "The frequencies of CD4+IFN-γ+TNF-α− and CD8+IL-10+ T cells showed the most positive associations with the parameters known to be indicators of a poor prognosis such as LNs involvement, larger tumor size and higher stage of the disease." (PMID 36376825, 2022). "Th2 cells can secrete multiple cytokines, such as IL-4, IL-5, IL-10, and IL-13, which are associated with inflammation and tumor-promoting functions." (PMID 36193495, 2022). "M2 macrophages are classically stimulated by cytokines IL-4, IL-13, IL-10, and M-CSF and are associated with reduction of inflammatory signals, resolution of the immune response, wound healing, and tumor promotion." (PMID 35264604, 2022). "TNBC cells have also been observed to secrete interleukin (IL)-4, IL-10, and other factors to promote tumor-associated macrophage polarization toward M2, which is associated with fast tumor progression." (PMID 35432487, 2022). "Synthesis of IL10 simultaneously enhanced antitumor immunity and inhibited tumor-associated inflammatory." (PMID 36618967, 2022).
tumor (continued). "CMV infection of the monocytes and neural stem cells generates IL-10 and induces the recruitment of the tumor microenvironment-associated monocytes (macrophages and microglial cells)." (PMID 36079151, 2022). "IL10-MSCs were injected subcutaneously into both necks of severe combined immune deficiency (SCID) mice to investigate tumor formation during a long-term observation period of 4 months." (PMID 35300585, 2022). "Tumor-associated macrophages also secrete IL-10, which maintains the increased Treg population in the tumor microenvironment." (PMID 36428581, 2022). "Several other factors produced by tumor or tumor-associated cells, like prostaglandin E2, extracellular adenosine, IL-10 and IL-6, further directly or indirectly prevent NK cell activation." (PMID 36045670, 2022). "STAT3 activation is associated with high expression of tumor promoting cytokines and growth factors such as IL-10, transforming growth factor (TGF)-β and vascular endothelial growth factor (VEGF)-A." (PMID 35865518, 2022). "The prevalence of M2 macrophages in the tumor tissues from Emilin-2−/− mice was consistent with a 100% increase of IL-10, one of the main M2-associated cytokines." (PMID 35148799, 2022). "Exosomes secreted by GC cells can guide monocytes into M2-characterized programmed cell death 1 (PD-1)-positive tumor-associated macrophages, upregulating the secretion of IL-10 and thus affecting the function of CD8+T cells." (PMID 36230816, 2022). "M2d macrophages are induced by the costimulation of the adenosine A2 receptor and TLR, expressing levels of IL-10 as well as IL-12, and characterized by presenting properties of tumor-associated macrophages that carry out angiogenesis and tumor progression." (PMID 35480895, 2022). "Tregs secreted cytokine IL-10, which is associated with poor prognosis in cancers, involving the activation of tumor-resident APC and suppression of effective T cell functions." (PMID 35585567, 2022). "Tumor-associated macrophages (TAMs) are shaped by chemokines such as IL-4, IL-10, and IL-13 to suppress antitumor immunity." (PMID 35493518, 2022). "Upon recruitment and activation of tumour-associated macrophages and myeloid-derived suppressor cells, these immune cells release IL-10 and TGF-β, and this concomitantly results in the recruitment of TREG cells which themselves produce IL-10 and TGF-β." (PMID 35359426, 2022). "Simultaneous expression of VEGF, IL-10, and arg-1 on tumor cells induces TIM-3 expression on BMDCs and tumor-associated DCs." (PMID 36713558, 2022). "IL-10, which is secreted by BC cells, leads to polarization and thus to an effect reversal on macrophages: normally anti-neoplastic, polarized M2 tumor-associated macrophages (TAMs) are pro-angiogenic and thus tumor-promoting." (PMID 35158964, 2022). "IL1β, IL-2, IL-12, TNF-α, and IFN-γ, known as Th1 cytokines, are associated with good prognosis in many malignancies, whereas Th2 cytokines (IL-4, IL-5, and IL-10) are associated with tumor growth and metastasis." (PMID 36090972, 2022). "We have observed that NK cells and macrophages are highly expressed in various metabolic subtypes, while tumor-associated macrophages (TAMs) produce IL-10 and TGF-β." (PMID 35800989, 2022). "Tumor cells, MDSCs, tumor-associated macrophages (TAMs), DCs, and Tregs, have all been found to generate IL-10 in the TME." (PMID 36703982, 2022). "Although an oversimplification, for charting purposes, the cytokines were split into three groups by their generalized tumor-destroying (IFN-γ, IL-2, and IL-5), tumor-promoting (IL-10 and IL-4), or SIRS-associated (IL-1β, IL-6, CXCL-1, and TNF-α) properties." (PMID 35465347, 2022). "IL-10 induces the proliferation of regulatory T cells and causes the transformation of macrophages to tumor growth-promoting M2-Mφ." (PMID 35154134, 2022). "Although it is mostly produced by tumor associated myeloid cells and Tregs, overall effects IL-10 on tumor immunity remain elusive." (PMID 36248808, 2022).